SNRK (SNF related kinase)
Description:
May play a role in hematopoietic cell proliferation or differentiation. Potential mediator of neuronal apoptosis.
Synonyms: KIAA0096; FLJ20224; HSNFRK
Tractability: Small molecule: a high-quality ligand is known; it belongs to a druggable protein family. Antibody: the Human Protein Atlas places it where antibodies can reach. PROTAC: it is named in the literature on targeted protein degradation; ubiquitination databases record sites on it; its protein half-life has been measured; a small molecule that binds it is known.
Target class: Kinase; Protein Kinase; Enzyme; CAMK protein kinase group
Gene: Protein-coding gene on chromosome 3 (43,286,510 to 43,424,764, forward strand). Ensembl gene ENSG00000163788.
Subcellular location: Nucleus
Subcellular location (Human Protein Atlas): Cell Junctions; Plasma membrane; Vesicles; Nucleoplasm
Gene Ontology:
Molecular function: ATP binding; magnesium ion binding; protein serine kinase activity; protein serine/threonine kinase activity; protein kinase activity
Biological process: protein phosphorylation; myeloid cell differentiation
Cellular component: nucleus
Genetic constraint (gnomAD): Loss-of-function variants: 4 observed, 47.87 expected, observed/expected ratio (o/e) 0.0836, 90% interval 0.04 to 0.19. The upper end of that interval is the gene's LOEUF score, 0.19, which puts it in group 1 of 6, group 1 being the genes least tolerant of losing a copy. Missense variants: 625 observed, 997.32 expected, observed/expected ratio (o/e) 0.63, 90% interval 0.59 to 0.67. Synonymous variants: 373 observed, 378.19 expected, observed/expected ratio (o/e) 0.99, 90% interval 0.9 to 1.07.
Homologues: Orthologues: chimpanzee SNRK (99% identical), macaque SNRK (99% identical), rabbit SNRK (98% identical), pig SNRK (95% identical), dog SNRK (95% identical), guinea pig SNRK (93% identical), mouse Snrk (89% identical), rat Snrk (89% identical), tropical clawed frog snrk (87% identical), zebrafish snrka (78% identical), Drosophila melanogaster Snrk (45% identical), Caenorhabditis elegans ZK524.4 (42% identical), and 3 more. Paralogues in human: SIK3 (25% identical), SIK1 (24% identical), SIK2 (24% identical), BRSK1 (21% identical), BRSK2 (21% identical), MELK (20% identical), NUAK2 (20% identical), PRKAA2 (20% identical), PRKAA1 (19% identical), NUAK1 (19% identical), HUNK (18% identical), NIM1K (17% identical), and 5 more.
Diseases named in the same sentence as SNRK in open-access papers:
SNRK is named in the same sentence as 22 diseases in open-access papers, as found by Europe PMC text mining. Sharing a sentence is not in itself a finding about the gene and the disease. The quoted sentences say what the papers report.
colon cancer (4 papers, 2020 to 2025). "SNRK expression was found to be decreased in human colon cancer tissues, while overexpression of SNRK inhibited colon cancer cell proliferation by upregulating calcyclin-binding protein (CacyBP) and promoting β-catenin degradation." (PMID 41141622, 2025). "Mechanistically, SNRK inhibits the proliferation of colon cancer cells through upregulation of calcyclin-binding protein (CacyBP) and β-catenin degradation." (PMID 32968716, 2020). "Moreover, SNRK increased CacyBP mRNA and protein and decreased β-catenin protein in HCT116 and RKO colon cancer cells." (PMID 40149719, 2025).
heart failure (4 papers, 2021 to 2025). Inability of the heart to pump blood at an adequate rate to meet tissue metabolic requirements. "We conclude that under nonischemic heart failure conditions, increased SNRK expression in the atria is associated with a cardioprotective mechanism by controlling the release of the profibrotic transforming growth factor-β1 factor." (PMID 40584789, 2025). "The precise mechanism underlying cardiomyocyte SNRK-driven repression of deleterious cardiac fibrosis in nonischemic heart failure-mediated cardiac repair and regeneration is not known." (PMID 40584789, 2025). "Together, our results demonstrated that the negative loop of circ-SNRK with SNRK regulates the energy metabolism in CMs, thus might be a potential therapeutic target for heart failure." (PMID 34621049, 2022). "The consequence of this negative feedback is to constrain the SNRK protein at an appropriate level, which suggests that the function of circSNRK with SNRK in regulating energy metabolism in cardiomyocytes could be a potential therapeutic target for heart failure." (PMID 39452835, 2024).
breast carcinoma (3 papers, 2021 to 2024). "One study has found that mutated LKB1 could alter several kinases pathways including SNRK, and it is associated with breast cancer in which it can affect the patient survival and the outcome of the treatment." (PMID 36268271, 2022). "In all breast cancer combined, high expression of LKB1, AMPK, LYK5, MARK1, MARK2, NUAK2, PAK1 (both probe sets), SIK1, SIK2, BRSK1, BRSK2, SNRK, and QSK was positively correlated with improved survival compared to low expression of these genes." (PMID 34084284, 2021). "In Luminal A breast cancers, the positive survival effects of AMPK, MARK3, PAK1, BRSK1, SNRK, and QSK are maintained in the pre-chemotherapy but not in the post-chemotherapy cohorts." (PMID 34084284, 2021).
myocardial infarction (3 papers, 2017 to 2022). Gross necrosis of the myocardium, as a result of interruption of the blood supply to the area, as in coronary thrombosis. "SNRK protein was also increased in ischaemic regions of dog hearts subjected to myocardial infarction, compared with non-ischaemic control regions." (PMID 28117339, 2017).
acute kidney injury (2 papers, 2022 to 2025). Sudden and sustained deterioration of the kidney function characterized by decreased glomerular filtration rate, increased serum creatinine or oliguria. "Furthermore, miR-223-3p in extracellular vesicles of human medulla ossium mesenchymal stem cells alleviate inflammation and pyroptosis in acute kidney injury (AKI) by targeting HDAC2 and enhancing SNRK transcription." (PMID 40372489, 2025).
cardiac hypertrophy (2 papers, 2020 to 2025). "Some of SNRK’s cardiac function are reminiscent of mitochondrial sirtuin proteins specifically SIRT3, wherein Sirt3 knockout mice are highly sensitive to stress, which leads to cardiac hypertrophy, fibrosis, and increased mortality." (PMID 32968716, 2020).
Infertility (2 papers, 2011 to 2024). "Some of the genes presented, such as CCSER1, GNAQ, NCOA2, SNRK, and TSPO, have been previously associated with fertility traits in livestock species or related to infertility in human patients (CEP78 and GPER1)." (PMID 38540441, 2024). "Interestingly, in rats SNRK has previously been suggested to be testis-specific making this a potential candidate in the infertility phenotype." (PMID 22145035, 2011).
Insulin resistance (2 papers, 2020 to 2024). Increased resistance towards insulin, that is, diminished effectiveness of insulin in reducing blood glucose levels. "Within the SNF-related serine/threonine-protein kinase (SNRK) subfamily, SNRK is the only member, and it plays a role in insulin resistance." (PMID 38892400, 2024). "The specific mechanism utilized by SNRK to prevent insulin resistance in adipose tissue is through protein phosphatase 2 regulatory subunit B’ delta (PPP2R5D) phosphorylation, which impacts PP2A activity and phosphorylation of AKT." (PMID 32968716, 2020).
Obesity (2 papers, 2022 to 2025). Accumulation of substantial excess body fat. "Human genetics analyses have revealed two single nucleotide polymorphisms within the SNRK gene associated with obesity risk in the United States population." (PMID 41141622, 2025). "Of note, the expression of SNRK is found to be associated with cancer disease and obesity." (PMID 36268271, 2022).
cardiomyopathy (1 paper, 2017). A disease of the heart muscle or myocardium proper. "First, we found that SNRK protein levels are increased in hearts from patients with cardiomyopathy relative to patients with normal cardiac function." (PMID 28117339, 2017).
diabetes mellitus (1 paper, 2022). A metabolic disorder characterized by abnormally high blood sugar levels due to diminished production of insulin or insulin resistance/desensitization. "In the ceRNA network, miR-103a-3p is elevated in the urine of patients with diabetes mellitus and upregulated in the plasma of patients with hypertension, and modulated SNRK/NF-κB/p65 signaling promotingangiotensin II–induced renal inflammation and fibrosis." (PMID 36138345, 2022).
hypertensive nephropathy (1 paper, 2020). Kidney damage that results from chronically elevated blood pressure; complications include glomerular damage resulting in proteinuria and hematuria. "In line with the fact that miR-103a-3p downregulates Snrk expression, kidneys of patients with hypertensive nephropathy expressed lower levels of SNRK compared to control kidneys." (PMID 32906849, 2020).
ovarian carcinoma (1 paper, 2022). A malignant neoplasm originating from the surface ovarian epithelium. "In addition to our findings, some investigators have reported that SNRK has been found to be expressed in ovarian cancer cell lines." (PMID 36268271, 2022).
tumor (5 papers, 2006 to 2024). "SNRK is phosphorylated and activated by the LKB1 serine/threonine-protein kinase that regulates cell polarity and functions also as a tumor suppressor." (PMID 16390543, 2006). "Five genes, ROBO4, SNRK, TM4SF1, FMO2 and TIMP3, found in this screen have been preferentially associated with capillary endothelial cells from mouse lung and TMBM expression was found specifically in tumour endothelial cells, but not normal endothelial cells." (PMID 16390543, 2006).
cancer (2 papers, 2022). A tumor composed of atypical neoplastic, often pleomorphic cells that invade other tissues. "The LC-LK CCPs are made of two or three nodes maximum and identified four genes (SNRK, BIRC5, HBB, and IL33) associated with the acquisition of the hallmarks of cancer." (PMID 36101460, 2022). "ReactomeFIViz enrichment analysis in Cytoscape showed that four genes (SNRK, BIRC5, HBB, and IL33) have evidence of their association with the acquisition of cancer characteristics." (PMID 36101460, 2022).
infection (1 paper, 2021). The state of being infected such as from the introduction of a foreign agent such as serum, vaccine, antigenic substance or organism. "This differential performance of cells from donator 1 connects to higher transcription levels of SNRK at 72 hpi in cells from donator 1 after infection with both the original SARS-CoV-2 and SARS-CoV-2 Δ382." (PMID 34960145, 2021).
SNRK also shares sentences with these, for which no sentence is quoted: angiosarcoma (3 papers); short bowel syndrome (2); colorectal cancer (1); Hypertension (1); prostate carcinoma (1); soft tissue sarcoma (1).